GSDMD (gasdermin D)
Diseases named in the same sentence as GSDMD in open-access papers (continued):
Sharing a sentence is not in itself a finding about the gene and the disease.
ZIKV infection (5 papers, 2022 to 2025). "Here, we found that the cellular gasdermin D (GSDMD) is required for the efficient death of a human GBM cell line caused by ZIKV infection." (PMID 36699618, 2023). "To understand the timeline of GSDMD-mediated cell death after ZIKV infection, we checked the GSDMD cleavage events in cells stably expressing the V5-tagged GSDMDs." (PMID 36699618, 2023). "We replaced the S residue of human GSDMD with the corresponding residue V found in murine and restored the SF268-GSDMD−/− cells with either the WT or S250V mutant for ZIKV infection." (PMID 36699618, 2023). "To test whether pyroptosis was responsible for the caspase-independent oncolysis upon ZIKV infection, we knocked down the expression of endogenous GSDMD in SF268 cells." (PMID 36699618, 2023). "In addition, GSDMD, a substrate of caspase-1, was cleaved to become cleaved GSDMD, an executor of pyroptosis, indicating that ZIKV infection activated inflammasomes, and induced pyrotosis, probably via a caspase-1-dependent canonical pathway." (PMID 35446851, 2022). "Thus, ZIKV infection triggered caspase- and GSDMD-mediated cytotoxicity in human GBM SF268 cells." (PMID 36699618, 2023). "Consequently, we determined whether caspase-1 and GSDMD cleavage resulting from activation of the NLRP3 inflammasome were induced by ZIKV infection." (PMID 37191498, 2023). "The pan-caspase inhibitor zVAD did not block the ZIKV-induced GSDMD-mediated cell injury, which suggests that ZIKV infection harmed the infected human GBM cells and disseminated GSDMD-mediated injury to nearby uninfected cells." (PMID 36699618, 2023). "The synchronized ZIKV infection revealed that WT, rather than GSDMD−/−, cells were more sensitive to the ZIKV killing effects." (PMID 36699618, 2023). "To clarify the roles of GSDMD in ZIKV infection without the effects of incomplete GSDMD knockdown, we knocked out endogenous GSDMD in SF268 cells by using the CRISPR-Cas9 system." (PMID 36699618, 2023).
alcohol use disorder (4 papers, 2022 to 2025). "Disulfiram (used to treat alcohol use disorder) has recently been identified as a potent GSDMD inhibitor." (PMID 35625908, 2022). "Disulfiram is FDA approved for the treatment of alcohol use disorder, due to its ability to inhibit aldehyde dehydrogenase, but it was recently shown that disulfiram also can block gasdermin D in macrophages." (PMID 35133984, 2022). "Additionally, NET inhibition rather than digestion also appears to be a promising approach to prevent ricin-induced acute lung injury, as indicated by an administration of Disulfiram, an FDA-approved gasdermin D inhibitor for the treatment of alcohol abuse, prevented signs of lung injury." (PMID 41023796, 2025).
anemia (4 papers, 2022 to 2025). A reduction in the number of red blood cells, the amount of hemoglobin, and/or the volume of packed red blood cells. "Instead, serum GSDMD was inversely related to erythrocyte count, which is consistent with observation on the gasdermin knockout preventing anemia development in animal models of some inflammatory diseases." (PMID 41007405, 2025). "Knocking out GSDMD in a mouse model of NOMID obviously reduced the symptoms of leukocytosis and anemia, indicating that GSDMD is a novel therapeutic target for NOMID." (PMID 37250902, 2023). "A similar improvement in anemia was recently demonstrated in FMF-KI mice upon deletion of gasdermin D, a pore-forming protein required for IL-1β release." (PMID 36494621, 2022). "Moreover, deletion of GSDMD in vivo completely rescued growth retardation, anemia, cytokine production, neutrophilia, and tissue damage secondary to autoinflammation seen in MefvV726A/V726A mice." (PMID 39335710, 2024).
aneurysm (4 papers, 2022 to 2024). Bulging or ballooning in an area of an artery secondary to arterial wall weakening. "The mRNA expression of the downstream NLRP3 pathway components caspase-1, IL-1β, and GSDMD is also increased in the aneurysm tissue compared to healthy vessels." (PMID 41541085, 2023). "Smooth muscle cell-specific deletion of gasdermin D also attenuated aneurysm diameter expansion and reduced AAA incidence in experimental AAAs created by subcutaneous Ang II infusion or topical application of elastase to aortic adventitia." (PMID 37371479, 2023). "This study further demonstrated the predictive accuracy of IL-1.ra/beta ratio for AWE, and IL-1.ra/beta ratio was significantly correlated with the relative level of GSDMD in aneurysm tissues." (PMID 35155635, 2022). "In human aneurysm specimens, we also found that both pyroptosis markers (NLRP3, GSDMD and CASP1) and circHipk3 were mainly concentrated in the adventitia of aneurysm tissue, which was the main site of macrophage infiltration." (PMID 39601144, 2024). "To determine if pyroptosis plays a role in human and mouse aneurysms, we evaluated markers of pyroptosis including NLRP3, CASP1, GSDMD and IL‐1β, and also analysed MMP2/9 in human aortic aneurysms and mouse AAA." (PMID 39601144, 2024). "Further, aneurysm tissue also demonstrated higher mRNA expression levels of the NLRP3 pathway components caspase-1, IL-1β, and GSDMD." (PMID 41541085, 2023). "Notably, the levels of serum IL-1β and IL-1.ra were correlated with the relative levels of GSDMD, MMP2 and CD68 in aneurysm tissues." (PMID 35155635, 2022).
cardiomyopathy (4 papers, 2022 to 2025). A disease of the heart muscle or myocardium proper. "By generating GSDMD global knockout mice, it has been found that GSDMD deficiency reduces Doxorubicin (Dox)-induced cardiomyopathy." (PMID 37766966, 2023). "In summary, these observations indicated GSDMD involvement in DOX-related cardiomyopathy." (PMID 36289195, 2022). "Collectively, these observations indicated that GSDMD KO in the heart is protective against DIC in both acute and chronic models of DOX cardiomyopathy." (PMID 36289195, 2022).
colon adenocarcinoma (4 papers, 2025). "Similarly, analysis of MSI scores demonstrated a significant positive association with GSDMD expression in cancers including Colon Adenocarcinoma (COAD)." (PMID 40491921, 2025). "Furthermore, axitinib 37 serves as a pyroptotic agents in colon adenocarcinoma through caspase-1/GSDMD activation and pancreatic adenocarcinoma through caspase-3/GSDMC activation." (PMID 39316325, 2025). "Furthermore, septacidin 76 is used as pyroptotic agent in colon adenocarcinoma through caspase-1/GSDMD activation." (PMID 39316325, 2025). "In colon adenocarcinoma (COAD) and pancreatic adenocarcinoma (PAAD) patients, GSDMD expression was also associated with Th1 infiltration, characterized by IFN-γ secretion." (PMID 40759573, 2025). "Furthermore, luteolin increases the expression of caspase‐1, interleukin (IL)‐1β, Gasdermin D, and induces pyroptosis, a form of cellular death in HT29 human colon adenocarcinoma cell line." (PMID 39830909, 2025).
colorectal tumor (4 papers, 2024 to 2025). "Loss of GSDMD resulted in reduced infiltration of immature myeloid cells, and increased numbers of macrophages in colorectal tumors." (PMID 38898209, 2024). "We also found reduced arginase 1 (Arg1) and COX2 expression in colorectal tumors that lack GSDMD, supporting the notion that GSDMD mediates the recruitment of MDSCs to tumors." (PMID 38898209, 2024). "They found that hypoxia can induce GSDMD FL to translocate into nucleus of colorectal tumor cells to interact with poly (ADP-ribose) polymerase-1 (PARP-1), which blocks DNA repair function of PARP-1 to accelerate apoptosis." (PMID 38429278, 2024). "We found decreased levels of NLRP3 protein and activated GSDMD in large colorectal tumors compared to small ones, suggesting the inefficiency of bacteria and their products reaching the core of large colorectal tumors." (PMID 38898209, 2024). "In both models, we observed robust cleavage of GSDMD in colorectal tumors, suggesting a potential involvement of GSDMD in CRC pathogenesis." (PMID 38898209, 2024). "Here, we show that GSDMD is activated in colorectal tumors of both human and mouse origins." (PMID 38898209, 2024). "In addition, NLRP3 inhibition also increased the population of F4/80+ macrophages in colorectal tumors, similar to what was observed in GSDMD knockout mice." (PMID 38898209, 2024). "We found that the transcriptional levels of GSDMA, GSDMC, and PJVK were significantly increased in human colorectal tumors; while, the expression of GSDMB, GSDMD, and GSDME remained unchanged." (PMID 40213993, 2025). "Based on this finding, we further examined GSDMD activation in tumor-infiltrating CD4+ T cells of colorectal tumor tissues derived from patients responsive and patients nonresponsive to anti–PD-1 immunotherapy." (PMID 40759573, 2025). "Consistently, ablation of GSDMD in colorectal tumors did not result in any change in the activation of caspase 1, or IL-1 family cytokines or formation of NLRP3 or ASC specks." (PMID 38898209, 2024).
hepatic (4 papers, 2020 to 2023). "In this study, globally Gsdmd-deficient mice were challenged with ConA to investigate the direct contribution of GSDMD to immune-driven hepatitis." (PMID 35972273, 2022).
leukocytosis (4 papers, 2022 to 2023). "To explore the mechanisms underlying GSDMD deficiency–conferred cardioprotection after AMI, and based on recent suggestions that GSDMD may play a role in neutrophil production/mobilization, we investigated leukocyte infiltration and leukocytosis in AMI." (PMID 34752417, 2022).
liver cirrhosis (4 papers, 2022 to 2023). "The circulating levels of GSDMD and IL-18 are significantly upregulated in patients with liver cirrhosis and are correlated with disease severity." (PMID 38002346, 2023). "The inhibitor of GSDMD, disulfiram, showed therapeutic effects for liver cirrhosis similar to SHED infusion." (PMID 35634294, 2022). "The important finding from this study is that GSDMD-induced pyroptosis was involved in murine liver cirrhosis." (PMID 35634294, 2022). "To verify the effects of pyroptosis on liver cirrhosis, we used disulfiram, a potent inhibitor of GSDMD, to treat liver cirrhosis." (PMID 35634294, 2022). "In summary, the present study demonstrated that SHED infusion attenuated liver damage by inhibiting the GSDMD-executed pyroptosis pathway in CCl4-induced liver cirrhosis." (PMID 35634294, 2022). "In a mouse model of CCl4-induced liver cirrhosis, a triggering role of pyroptosis in the progression of liver injury was also shown, as demonstrated by the high expression of gasdermin D (GSDMD), caspase 1, and NLRP3 and the pro-inflammatory cytokine IL-1β in the animals’ livers." (PMID 37894893, 2023). "The expression of GSDMD and Caspase-1 was increased in the liver cirrhosis group." (PMID 35634294, 2022). "SHED infusion and the targets on GSDMD may be potential novel therapeutic strategies for liver cirrhosis." (PMID 35634294, 2022). "However, the role of GSDMD in liver cirrhosis remains unclear." (PMID 35634294, 2022). "In the present study, we evaluated the therapeutic effect of SHED on CCl4-induced mouse liver cirrhosis and revealed that SHED administration attenuated liver cirrhosis by alleviating GSDMD-mediated pyroptosis and inflammation." (PMID 35634294, 2022). "Immunohistochemical assays showed that NLRP3, GSDMD, caspase-1 and CK19 were more highly expressed in the liver cirrhosis group than in the other groups, and the levels in the medium and high dose Exo-rBMMSC groups were dramatically decreased." (PMID 36552767, 2022). "Mechanistically, NLRP3 inflammasome-activated GSDMD and its pyroptosis were upregulated in liver cirrhosis, while SHED infusion could suppress the expression of GSDMD and Caspase-1, resulting in reduced hepatocyte pyroptosis and inflammatory cytokine IL-1β release." (PMID 35634294, 2022).
lung squamous cell carcinoma (4 papers, 2022 to 2025). "GSDMD expression was lower in several cancers, including KICH, lung squamous cell carcinoma (LUSC), and prostate cancer (PRAD), compared to normal tissues." (PMID 36003332, 2022). "However, the expression of GSDMD doesn’t show any linkage with survival rates in lung squamous cell carcinoma (LUSC), suggesting the potential of GSDMD as a standalone prognostic indicator for LUAD." (PMID 38304430, 2024).
memory impairment (4 papers, 2021 to 2024). "In AD, sodium houttuyfonate (SH), one of the major extracts from houttuynia cordata, has been shown to inhibit NLRP3/GSDMD, a pathway responsible for memory impairment, inflammation, and pyroptosis." (PMID 36713841, 2023). "In the present study, we confirmed that SH could ameliorate Aβ1-42-induced memory impairment, neuroinflammation, and pyroptosis through inhibiting the NLRP3/GSDMD pathway in AD." (PMID 34188608, 2021). "In summary, we demonstrated that SH could ameliorate Aβ1-42-induced memory impairment, neuroinflammation, and pyroptosis through inhibiting the NLRP3/GSDMD pathway in AD." (PMID 34188608, 2021).
neonatal-onset multisystem inflammatory disease (4 papers, 2020 to 2023). "Loss of GSDMD expression rescues mice with a D301N Nlrp3 mutation causing the Neonatal-onset multisystem inflammatory disease (NOMID) as well as mice with a neutrophil-specific A350V Nlrp3 mutation, which is associated with Muckle-Wells Syndrome." (PMID 37664463, 2023). "This dual activity of imiquimod appears even more attractive in view of the recent description of an inflammatory disorder (NOMID, neonatal-onset multisystem inflammatory disease) caused by GASDERMIN D (GSDMD) release and pyroptosis following inflammasome activation." (PMID 32104502, 2020).
pancreatitis (4 papers, 2021 to 2025). Inflammation of the pancreas. "Therefore, after GQD intervention, the production of NLRP3 can be inhibited, thereby reducing the synthesis of Caspase-1 and GSDMD, lowering the release of inflammatory factors such as IL-1β and IL-18, and increasing IL-10 levels, thereby preventing the progression of post ERCP pancreatitis." (PMID 40620677, 2025).
pneumonia (4 papers, 2022 to 2026). An acute, acute and chronic, or chronic inflammation focally or diffusely affecting the lung parenchyma, caused by an infection in one or both of the lungs (by bacteria, viruses, fungi, or mycoplasma.). "Although combined oseltamivir and linezolid treatment failed to fully alleviate lung injury, the inclusion of disulfiram, a GSDMD pore formation inhibitor, significantly ameliorated pneumonia symptoms and reduced inflammatory responses." (PMID 41927528, 2026).
preeclampsia (4 papers, 2020 to 2025). Preeclampsia is a hypertensive disorder of pregnancy that is characterized by new-onset hypertension with proteinuria presenting after 20 weeks of gestation, and depending on mild or severe forms may initially present with severe headache, visual disturbances, and hyperreflexia. "Activation of Caspase 1 in the inflammasome pathway can also result in pyroptosis by cleavage of Gasdermin D, as also observed in the placentae of patients with preeclampsia." (PMID 37047793, 2023). "Under pathological conditions (such as preeclampsia and chronic villitis), macrophages trigger the secretion and synthesis of sFLT-1 through a pro-inflammatory cascade involving NLRP3 inflammasomes and Gasdermin D (GSDMD)." (PMID 41050693, 2025).
prostate carcinoma (4 papers, 2022 to 2025). A carcinoma that arises from epithelial cells of the prostate gland. "In this study, we show that GSDMD expression is upregulated in human breast, kidney, liver, and prostate cancer." (PMID 39224600, 2024). "GSDMD mRNA expression was upregulated in several types of cancer, including breast, kidney, liver, and prostate cancer." (PMID 39224600, 2024).
renal cell carcinoma (4 papers, 2021 to 2024). "A total of 14 normal human renal specimens (7 males and 7 females) were collected from the patients who underwent renal cell carcinoma radical surgery to evaluate the basal expression levels of GSDMD and GSDME in renal tubular epithelial cells." (PMID 38388468, 2024). "Subsequently, we found that GSDMD also has certain significance in the diagnosis of renal cell carcinoma through the ROC curve." (PMID 37483501, 2023). "The results of EMT correlation analysis and enrichment analysis showed that GSDMD was correlated with genes and pathways related to invasion and metastasis of renal cell carcinoma." (PMID 37483501, 2023). "The results showed that overexpression of GSDMD promoted the proliferation, invasion, and migration of renal cell carcinoma but decreased the apoptosis ability of renal cell carcinoma." (PMID 37483501, 2023). "Meanwhile, the expression of GSDMD was correlated with disease-free survival and overall survival of renal cell carcinoma (p < 0.05)." (PMID 37483501, 2023). "The results showed that the expression of GSDMD in renal cell carcinoma was higher than that in normal renal tissue, and there were differences in the clinical stage and pathological stage." (PMID 37483501, 2023). "First, through the biological information platform database, the expression of GSDMD in renal cell carcinoma and normal renal tissue and its relationship with clinical stage and prognosis were analyzed." (PMID 37483501, 2023). "The expression of GSDMD in renal cell carcinoma by immunohistochemistry and in vitro cell experiments was confirmed." (PMID 37483501, 2023). "In addition, we verified that the expression of GSDMD in renal cell carcinoma was significantly higher than that in normal kidney tissue by immunohistochemistry and cell experiments in vitro, which had statistical differences." (PMID 37483501, 2023). "Finally, in order to prove the role of GSDMD in the occurrence and development of renal cell carcinoma, we utilized stable cell lines of LV/LV-NC and si/si-NC and carried out in vitro functional experiments such as MTT proliferation assay, Transwell invasion and migration assay, and apoptosis assay." (PMID 37483501, 2023).
sickle cell disease (4 papers, 2023 to 2025). Sickle cell anemias are chronic hemolytic diseases that may induce three types of acute accidents: severe anemia, severe bacterial infections, and ischemic vasoocclusive accidents (VOA) caused by sickle-shaped red blood cells obstructing small blood vessels and capillaries. "Emerging evidence underscores the pivotal role of Gasdermin D (GSDMD), the pyroptosis execution protein, in facilitating NETs generation during bacterial infection, sickle cell disease, and other pathological conditions." (PMID 38436813, 2024). "Notably, while GSDMD-NETs have been implicated in thrombosis during non-inflammatory conditions such as sickle cell anemia, their role in SIC pathogenesis remains underexplored." (PMID 40766307, 2025).
skin cutaneous melanoma (4 papers, 2022 to 2023). "GSDMD mRNA levels differed significantly between the clinical stages of KIRC, skin cutaneous melanoma, and STAD, but were higher in the more advanced stages of KIRC." (PMID 36003332, 2022). "Conversely, high expression of PANoptosis genes was beneficial in skin cutaneous melanoma (SKCM), with ZBP1, NLRP1, CASP8 and GSDMD expression consistently having positive prognostic effects." (PMID 36329783, 2022).
thrombosis (4 papers, 2022 to 2024). "Furthermore, in a mouse model of blood flow restriction‐induced venous thrombosis, deletion of caspase‐1 and GSDMD, but not caspase‐11, protected mice against venous thrombosis." (PMID 35569038, 2022).